NINL (ninein like)
Description:
Involved in the microtubule organization in interphase cells. Overexpression induces the fragmentation of the Golgi, and causes lysosomes to disperse toward the cell periphery; it also interferes with mitotic spindle assembly. Involved in vesicle transport in photoreceptor cells (By similarity). May play a role in ovarian carcinogenesis.
Synonyms: KIAA0980; NLP
Tractability: PROTAC: UniProt records ubiquitination sites on it; ubiquitination databases record sites on it.
Gene: Protein-coding gene on chromosome 20 (25,451,594 to 25,585,586, reverse strand). Ensembl gene ENSG00000101004.
Subcellular location: Cytoplasm, cytoskeleton, microtubule organizing center, centrosome; Cytoplasm
Subcellular location (Human Protein Atlas): Primary cilium; Vesicles; Cytokinetic bridge; Cytosol; Microtubules; Nucleoplasm
Pathways (Reactome):
Cell Cycle: AURKA Activation by TPX2; Loss of Nlp from mitotic centrosomes; Loss of proteins required for interphase microtubule organization from the centrosome; Recruitment of NuMA to mitotic centrosomes; Recruitment of mitotic centrosome proteins and complexes; Regulation of PLK1 Activity at G2/M Transition
Organelle biogenesis and maintenance: Anchoring of the basal body to the plasma membrane
Gene Ontology:
Molecular function: protein binding; calcium ion binding
Biological process: microtubule anchoring at centrosome
Cellular component: centrosome; cytoplasm; cytosol
Genetic constraint (gnomAD): Loss-of-function variants: 144 observed, 149.15 expected, observed/expected ratio (o/e) 0.97, 90% interval 0.84 to 1.11. The upper end of that interval is the gene's LOEUF score, 1.11, which puts it in group 4 of 6, group 1 being the genes least tolerant of losing a copy. Missense variants: 1,814 observed, 1,758.2 expected, observed/expected ratio (o/e) 1.03, 90% interval 0.99 to 1.07. Synonymous variants: 796 observed, 736.99 expected, observed/expected ratio (o/e) 1.08, 90% interval 1.02 to 1.14.
Homologues: Orthologues: chimpanzee NINL (97% identical), macaque NINL (92% identical), dog NINL (63% identical), rabbit NINL (62% identical), rat Ninl (61% identical), mouse Ninl (61% identical), guinea pig NINL (50% identical), tropical clawed frog ninl (42% identical), zebrafish ninl (32% identical), Drosophila melanogaster Nin (15% identical), Caenorhabditis elegans noca-2 (10% identical). Paralogues in human: NIN (30% identical).
Diseases named in the same sentence as NINL in open-access papers:
NINL is named in the same sentence as 22 diseases in open-access papers, as found by Europe PMC text mining. Sharing a sentence is not in itself a finding about the gene and the disease. The quoted sentences say what the papers report.
autism (3 papers, 2019 to 2025). Persistent deficits in social interaction and communication and interaction as well as a markedly restricted repertoire of activity and interest as well as repetitive patterns of behavior. "Our analysis supports the role of several genes/loci associated with autism (e.g., NRXN1, ADNP, 22q11 deletion) and identified new truncating (e.g., GRIK2, ROBO1, NINL, and IMMP2L) or recessive deleterious variants (e.g., KIRREL3 and CNTNAP2) affecting autism-associated genes." (PMID 30675382, 2019).
breast carcinoma (3 papers, 2015 to 2022). "Upregulated NINL mRNA and protein expression have been observed in several types of human tumors, such as head and neck squamous cell carcinoma (HNSCC), breast cancer, ovarian cancer, and lung cancer." (PMID 35719990, 2022).
ciliopathy (2 papers, 2015). A genetic disorder of the cellular cilia or the cilia anchoring structures, the basal bodies, or of ciliary function. "NINL, an important interaction partner of three ciliopathy-associated proteins (lebercilin, USH2A and CC2D2A), was previously shown to associate with this motor complex." (PMID 26485514, 2015). "The more severe phenotype only of the individual carrying causal CC2D2A mutations and an additional NINL truncating variant suggests that deleterious variants in NINL may act as genetic modifiers specifically of CC2D2A-caused ciliopathies such as Joubert syndrome." (PMID 26485645, 2015). "Ninein-like protein (NINL) is known to associate with this motor complex and is an important interaction partner of the ciliopathy-associated proteins lebercilin, USH2A and CC2D2A." (PMID 26485514, 2015). "NINL has been previously shown to bind several other ciliopathy proteins present at the base of cilia, specifically LCA5 and USH2A, suggesting that it may play a more pivotal role in vesicular trafficking in photoreceptors than CC2D2A." (PMID 26485645, 2015).
Joubert syndrome (2 papers, 2015 to 2018). Joubert syndrome (JS) is characterized by congenital malformation of the brainstem and agenesis or hypoplasia of the cerebellar vermis leading to an abnormal respiratory pattern, nystagmus, hypotonia, ataxia, and delay in achieving motor milestones. "A heterozygous variant in NINL has been proposed to act as a genetic modifier in a patient with a severe form of Joubert syndrome caused by mutations in CC2D2A." (PMID 29974258, 2018). "3364C>T (p.P1122S), previously shown to be causal for Joubert syndrome, and a heterozygous NINL frameshift mutation leading to a stop codon after 43 amino acids (c.3020delC, p.P1007Lfs*43) (and no other rare deleterious variant in any of the known JS genes)." (PMID 26485645, 2015). "Finally, we describe an individual with Joubert syndrome, in whom combined CC2D2A and NINL mutations result in an enhanced phenotype, illustrating the impact of the detected interaction on the disease." (PMID 26485645, 2015). "This hypothesis is also supported by the lack of bi-allelic NINL mutations in a large human cohort of Joubert syndrome." (PMID 26485645, 2015). "However, the physical and genetic interaction in zebrafish identified in this work substantially strengthen the significance of this finding and suggest that deleterious variants in NINL may indeed enhance the retinal and renal phenotype in individuals with CC2D2A-associated Joubert syndrome." (PMID 26485645, 2015). "While no bi-allelic rare deleterious NINL variants were identified in our JBTS cohort, we did find heterozygous NINL mutations in individuals with Joubert syndrome." (PMID 26485645, 2015).
coloboma (1 paper, 2015). An abnormality in which a part of a structure in one or both eyes is missing. "Given the known association between TMEM67 mutations and coloboma, this additional feature is most likely explained by the causal gene mutations, while the additional NINL variant appears to have no obvious effect on the phenotype in individual UW57-3." (PMID 26485645, 2015).
Hodgkins lymphoma (1 paper, 2021). A heterogeneous group of malignant lymphoid neoplasms of B-cell origin characterized histologically by the presence of Hodgkin and Reed-Sternberg (HRS) cells in the vast majority of cases. "M1 macrophages from HS2 patient showed increased levels of NINL and SNHG5, which have been associated with Hodgkin’s lymphoma lymphocytic-histiocytic predominance." (PMID 33284430, 2021).
viral infection (1 paper, 2022). "Using NINL knockout (KO) cells, we find that NINL is important for limiting viral infection, especially in the presence of the antiviral signaling cytokine, type I interferon (IFN)." (PMID 36222652, 2022). "Cleavage of ninein-like (NINL) during viral infection prevents dynein-dependent transport of an intracellular cargo." (PMID 36222652, 2022). "Compellingly, cleavage of NINL by 3Cpro during viral infection disrupts the NINL-mediated transport of a heterologous cargo." (PMID 36222652, 2022). "Finally, to determine whether viral infection could also disrupt NINL-mediated trafficking, we infected cells with CVB3 following transfection of PEX3-mEmerald-FKBP, and WT NINL or the uncleavable NINL triple mutant." (PMID 36222652, 2022).
infection (16 papers, 2015 to 2025). The state of being infected such as from the introduction of a foreign agent such as serum, vaccine, antigenic substance or organism. "Closely examining the gene sequence for NINL across primates highlighted an evolutionary signature characteristic of host-virus genetic conflicts; this suggests that the protein may be used by viruses to reproduce, or by cells to fend off infection." (PMID 36222652, 2022). "To evaluate this hypothesis, we generated a human A549 cell line that lacked NINL (NINL KO) as A549 cells are susceptible to infection with many viruses and mount an effective antiviral response after treatment with IFN." (PMID 36222652, 2022). "Using immunofluorescence staining, we confirmed the recruitment of NINL and BICDL2 to Shigella infection foci (possibly on the IAMs) at 30 min post-infection (respectively)." (PMID 38316786, 2024). "Consistent with the results we obtained with transfected 3Cpros, we observed cleavage of NINL at species-specific sites 231, 827, and 1032 when we infected with CVB3, and little to no cleavage upon EMCV infection." (PMID 36222652, 2022).
tumor (5 papers, 2018 to 2022). "GSE32018 dataset validation results showed that NINL expression differed significantly between tumor and normal tissues, and subgroup analysis samples from TCGA datasets demonstrated that NINL expression was associated with age and stage." (PMID 35719990, 2022). "Similarly, structural centrosome aberrations closely resembling those seen in tumours can be triggered by overexpression of Ninein-like protein (NLP), a PCM component implicated in MT anchoring during interphase of the cell cycle." (PMID 29899122, 2018). "While the rapid onset of radiation-induced lymphoma observed in NINL transgenic mice also confirms an oncogenic role for this gene, there is almost no information on how NINL expression impacts human tumor survival." (PMID 35719990, 2022).
cancer (3 papers, 2018 to 2022). A tumor composed of atypical neoplastic, often pleomorphic cells that invade other tissues. "Survival analysis showed that high NINL expression was a risk factor for overall survival (OS) and disease-specific survival (DSS) within older patients and those with advanced-stage cancer." (PMID 35719990, 2022). "Although upregulated NINL mRNA and protein expression have been observed in several types of human cancer, the potential function and prognostic role of NINL in DLBCL remains unknown." (PMID 35719990, 2022). "GSEA showed that NINL is significantly enriched during JAK-STAT signaling, PD-L1 expression and PD-1 checkpoint pathway in cancer, NF-κB signaling, and MAPK signaling." (PMID 35719990, 2022). "To comprehensively understand these three lncRNAs (BOLA3-AS1, AC124067.4, and AL161772.1) and four target RNAs (NINL, SALL4, TNFSF11, PHYHIPL), we performed differential expression, cancer stemness, immune subtype, TME infiltration, and drug sensitivity analyses." (PMID 34746134, 2021).
NINL also shares sentences with these, for which no sentence is quoted: fungal infection (3 papers); liver cancer (2); lung carcinoma (2); Ataxia (1); colorectal cancer (1); developmental delay (1); diffuse large B-cell lymphoma (1); genetic disorder (1); head and neck squamous cell carcinoma (1); invasive breast carcinoma (1); Meckel syndrome (1); ovarian carcinoma (1).